VIM (vimentin)
Diseases named in the same sentence as VIM in open-access papers (continued):
Sharing a sentence is not in itself a finding about the gene and the disease.
adenoma (21 papers, 2011 to 2025). A neoplasm arising from the epithelium. "Regarding location, in healthy tissue, vimentin expression is only perinuclear, while carcinoma shows significant cytoplasmic expression, and adenomas and hyperplasias show a combination of both patterns." (PMID 40149663, 2025). "Differently, the upregulation of vimentin in the adenomas of Aspirin-treated FAP patients is an unfavorable effect." (PMID 37173923, 2023). "Among the proteins detected in adenomas at baseline and after the Aspirin treatment, the changes in vimentin and HBB (hemoglobin subunit beta) were the most relevant responses to the drug treatment." (PMID 37173923, 2023). "The fraction of vimentin-positive parenchymal cells increased from 9.3% in normal tissues to 11.7% in multiglandular parathyroid disease, 19.3% in adenomas and 36.8% in carcinoma." (PMID 35805976, 2022). "Western blot protein analysis of the adenoma cell lines indicated higher expression of e-cadherin in wild type adenoma cells and higher expression of COX2 and VIM in FZD9-/- adenoma cells." (PMID 35924166, 2022). "The limited data on adenomas confirmed stromal reactivity but remained controversial in regard to the presence of vimentin in parenchyma." (PMID 35805976, 2022). "The same change in CTC counts was observed during the second recurrence of the adenoma, and a subgroup of CTCs, cell surface vimentin-positive CTCs, was significantly increased." (PMID 34745999, 2021). "The results showed that these PCNA positive proliferative stromal cells were mostly identified as vimentin positive fibroblasts in the adenoma/CRC stroma." (PMID 28484082, 2017). "When the density of vimentin positive fibroblasts was graded, the grading scores were higher in adenomas (grey bar) and CRCs (black bar) relative to controls (white bar), although statistical significance was not reached." (PMID 28484082, 2017). "In a recent work, we investigated WIF1, ALX4, and vimentin methylation in either urine or serum samples of 247 patients (90 patients with neoplasia and 157 control subjects normal colonoscopy or having small adenomas less than 1 cm)." (PMID 25221563, 2014). "N-myc downstream regulated gene 4 (NDRG4) could be also considered as a significant diagnostic marker gene in CRC (DOR: 24.37; 95%CI, 10.11–58.73) and Vimentin (VIM) in adenoma (DOR: 15.21; 95%CI, 2.72–85.10)." (PMID 30024936, 2018). "Enhanced colorectal TXA2 generation could contribute to the upregulation of vimentin in adenomas." (PMID 37173923, 2023). "Besides, NDRG4 and VIM could also be considered as significant diagnostic marker genes in CRC and adenoma, respectively." (PMID 30024936, 2018). "The results of double IHC demonstrated that many of the PCNA positive cells in the control, adenoma and CRC stromal cells were vimentin positive fibroblasts and confirmed that vimentin positive fibroblasts in the adenoma/CRC stroma might have a high proliferative capacity." (PMID 28484082, 2017). "Cell lines derived from intestinal adenomas of vimentin KO‐Apcmin mice are also expected to show greater sensitivity to HDACis and a less pronounced EMT phenotype, compared to cells derived from Apcmin adenomas." (PMID 27072512, 2016). "IHC staining of unmatched normal colon, adenoma, and CRC patient samples for TLR4, vimentin, and CD68 was performed in a limited cohort to identify myofibroblasts and macrophages, respectively." (PMID 24887394, 2014). "The combination of vimentin, OMSR, and TFPI2 methylation on stool-DNA from 107 individuals detected 86.7% of CRC and 76.5%, the adenoma, the specificity was 86.7%." (PMID 25221563, 2014). "One was the panel consisting of methylated BMP3/NDRG4/VIM/TFPI2/mutant KRAS, β-actin, and Hb-level (and later refined and commercialized as Cologuard®), which in stool detected CRC with 87% sensitivity, adenoma with 82% sensitivity, and demonstrated a specificity of 93%." (PMID 33030559, 2021).
adenoma (continued). "The results of vimentin IHC showed that fibroblasts were observed in the whole stroma within both the pericryptal and non-pericryptal regions in adenoma, CRC and control group sections." (PMID 28484082, 2017). "Loss of epithelial markers, (CK20, CDX2 and E-cadherin) and intense vimentin expression was observed in RCTs but neither in the normal mucosa or adenomas." (PMID 23425390, 2013). "The matched normal mucosa and all adenomas tested, in contrast, were negative for vimentin and positive for epithelial markers." (PMID 23425390, 2013). "The progression from normal intestinal mucosa to adenoma (adenomatous mucosa) and finally to adenocarcinoma in CRC is closely correlated with the EMT process and changes in the expression of a series of genes, such as E-cadherin, vimentin, and β-catenin." (PMID 21702981, 2011). "The upregulation of vimentin in adenomas of some Aspirin-treated FAP patients could identify nonresponders to Aspirin." (PMID 37173923, 2023). "In fact, the progression from normal intestinal mucosa to adenoma (adenomatous mucosa) and finally to adenocarcinoma in CRC is closely correlated with the EMT process and changes in the expression of a series of genes, such as E-cadherin, vimentin, and β-catenin." (PMID 27662663, 2016). "In addition, we have also observed an increase in cells positive for stem-like markers in the adenoma/CRC stroma that accompanied by an active proliferation rate in the tumor stromal cells, and many of the proliferative stromal cells were identified as vimentin positive fibroblasts." (PMID 28484082, 2017).
Alzheimer disease (20 papers, 2011 to 2025). A progressive, neurodegenerative disease characterized by loss of function and death of nerve cells in several areas of the brain leading to loss of cognitive function such as memory and language. "Intermediate filament protein vimentin (Vim) is a well-established marker for reactive astrocytes and has been closely associated with Alzheimer’s disease (AD)." (PMID 40243407, 2025). "Starting at month-6, this upregulated protein set includes neuroinflammatory-related proteins like complement C4-B, glial fibrillary acidic protein, protein-arginine deiminase type-2, vimentin, and vitronectin that have long been associated with Alzheimer’s disease." (PMID 35944844, 2022). "Targeting of vimentin is, therefore, potentially interesting as a new therapeutic approach to treat patients with Alzheimer's disease." (PMID 35002531, 2022). "The high citrullination of GFAP and vimentin with the abnormal accumulation of citrullinated peptides has been detected in the hippocampus of patients with Alzheimer's disease (AD)." (PMID 31886309, 2019). "Nevertheless, vimentin is discussed to be also upregulated as a damage-response mechanism in neurons in neurodegenerative disease like Huntington or Alzheimer disease, whereby vimentin is involved in neurite extension and synaptic recovery." (PMID 28841900, 2017). "Neuronal expression of vimentin (UniprotKB P08670), a cytoskeletal protein, is seen in Alzheimer disease, and there is evidence that neurons express vimentin as a damage-response mechanism." (PMID 28765563, 2017). "It perhaps is due to decreased expression of factors that are required to maintain neuronal homeostasis, such as decreased expression of vimentin that has damage response mechanisms that Alzheimer’s disease develops." (PMID 27875990, 2016). "Vimentin- immunoreactivity in astrocytes, macrophages and microglia becomes intensely positive in areas of brain affected by Alzheimer’s disease, multiple sclerosis, Pick’s disease, amyotrophic lateral sclerosis and cerebral infarction patients." (PMID 27875990, 2016). "Anti-stress responses gets weakened with age, this in turn also contributes to the development of Alzheimer’s disease such as Vimentin, Carbonic anhydrases, HSPs, SAPK." (PMID 27875990, 2016). "Furthermore, citrullinated vimentin was found in the brain tissues of patients with Alzheimer’s disease (AD) and sporadic Creutzfeldt-Jakob disease (sCJD)." (PMID 34116679, 2021). "Citrullinated GFAP and vimentin have been noted in Alzheimer’s disease patient." (PMID 30071078, 2018). "Anti-stress responses gets weakened with age, this in turn also contributes to the development of Alzheimer’s disease such as Vimentin has decreased expression in Alzheimer’s disease but over-expressed in Cancer, Carbonic anhydrases are increased in Cancers while decreased in AD brains." (PMID 27875990, 2016). "Upregulation of neuronal vimentin, on the other hand, may also take place since it was observed in lesioned sciatic nerve fibers as well as in neurons of the cerebral cortex, cerebellum, and hippocampus affected by Alzheimer’s disease." (PMID 33240046, 2020). "Finally, age is the greatest risk factor for Alzheimer’s disease development, and aging has been shown to induce astrocyte senescence, a cellular state characterized by hypertrophy, secretion of pro-inflammatory proteins, and increased expression of GFAP and vimentin." (PMID 37533101, 2023). "In the context of Alzheimer’s disease, the glial fibrous acidic protein (GFAP) and vimentin are identified as PAD2 major substrates, at the level of the hippocampus, where PAD2 is also immunolocalized." (PMID 33228136, 2020). "Vimentin is expressed in injured cultured DRG neurons, and in neurons during Alzheimer disease pathogenesis." (PMID 33250705, 2020). "As vimentin might assist the internalization of GIIA sPLA2 into neurons, this suggests why GIIA sPLA2 is involved in the aetiology of Alzheimer's disease." (PMID 35002531, 2022).
Alzheimer disease (continued). "Aggresomes, observed in Alzheimer’s disease cells in condition of proteotoxic stress, represent the dynamic recruitment of unfolded proteins via the microtubule network to the microtubule organizing center (MTOC) where vimentin as a “cage” takes place around these aggregated proteins." (PMID 36898995, 2023). "Thereafter, abundant proteins, such as myelin basic protein (MBP), fibrin, vimentin and GFAP, were also demonstrated to be targets of this post-translational modification, in several pathological contexts, such as multiple sclerosis, rheumatoid arthritis and Alzheimer’s disease." (PMID 33228136, 2020).
atherosclerosis (20 papers, 2011 to 2025). A disease characterized by the build-up of fatty material and calcium deposition in the arterial wall resulting in partial or complete occlusion of the arterial lumen. "Of these, VIM (vimentin) is a cytoskeletal intermediate filament protein positively linked to atherosclerosis and thrombosis." (PMID 38649659, 2024). "Anti-CCP antibodies are associated with early subclinical atherosclerosis and promote atherosclerotic plaque formation by targeting citrullinated sarcomeric proteins, fibrinogen, and vimentin." (PMID 37763669, 2023). "Among the 526 upregulated DEGs, were several well‐established genes associated with atherosclerosis plaques, such as matrix Gla protein, VIM, and B2M (Fig EV4D)." (PMID 38031960, 2023). "This is in agreement with other findings that showed that vimentin deficiency attenuates atherosclerosis in mice." (PMID 37475865, 2023). "In the current study, we performed experiments to evaluate how vimentin deficiency affects macrophage foam cell formation and atherosclerosis." (PMID 35656400, 2022). "In conclusion, we identified vimentin as a miR-144 target and describe its potential association with increased atherosclerosis in miR-144 KO mice fed an HFD." (PMID 32273567, 2020). "We therefore investigated if miR-144 KO mice, which displayed increased circulating vimentin, are more susceptible to atherosclerosis." (PMID 32273567, 2020). "Vimentin deficiency in macrophages has been shown to attenuate atherosclerosis in mice." (PMID 32273567, 2020). "The function of secreted or cell surface expressed vimentin is unclear but is associated with ageing and atherosclerosis, and potentially enhances a pro-inflammatory phenotype; vimentin secretion has been observed by activated macrophages in a protein kinase C (PKC)-dependent mechanism." (PMID 21182193, 2011). "Western blotting showed that CD31 and VE-Cadherin expression was declined, but α-SMA and vimentin expression was raised in atherosclerosis model group; however, these alterations were abrogated by SB431542." (PMID 38424494, 2024). "In summary, our current study demonstrated that vimentin-deficient macrophages uptake less oxLDL via decreased membrane localization of CD36 and thus CD36-deficiency in macrophages reduces development of atherosclerosis." (PMID 35656400, 2022). "In one study, overexpression of IL-37 reduced SMA and Vimentin expression in the aorta in atherosclerosis." (PMID 35602104, 2022). "Our current study aims to reveal functions of vimentin in macrophage foam cell formation, the critical stage of atherosclerosis." (PMID 35656400, 2022). "Here we discuss current concepts of the participation of vimentin filaments in the vital activity and functioning of endothelial cells, as well as the role of vimentin in the development of inflammatory processes and atherosclerosis." (PMID 35453578, 2022). "Recent research has demonstrated evidence for the functional involvement of vimentin intermediate filaments in the physiological functions of endotheliocyte and the development of inflammatory processes and atherosclerosis." (PMID 35453578, 2022). "Our study suggests a new therapeutic strategy for the treatment of atherosclerosis by revealing a new function of vimentin in macrophages." (PMID 35656400, 2022). "We are thus the first to report that vimentin is a target of miR-144 and have confirmed a functional relationship with atherosclerosis in miR-144 KO mice." (PMID 32273567, 2020). "The macrophage foam cells play a critical role in the occurrence and development of atherosclerosis, but the role of vimentin in this process is still unclear." (PMID 30451917, 2018). "A report also demonstrated high expression of vimentin in growth factor exposed smooth muscle cells which are involved in atherosclerosis." (PMID 22879973, 2012). "On the other hand, it is known that microRNA miR-144 may be a regulator of atherosclerosis development via changes in vimentin signaling." (PMID 35453578, 2022).
atherosclerosis (continued). "Moreover, the soluble vimentin acts as an indicator of the state of the cardiovascular system, and the involvement of vimentin in the development and course of atherosclerosis has been demonstrated." (PMID 35453578, 2022). "We concluded that vimentin promotes atherosclerosis in hypercholesterolemic mice." (PMID 35656400, 2022). "In addition to in vitro experiments, our in vivo experiments using vimentin null (Vim–/–) bone marrow transplantation into hypercholesterolemic mice confirmed the atherosclerosis-promoting effect of vimentin." (PMID 35656400, 2022). "E-cadherin and vimentin are reported to participate in the pathogenesis of atherosclerosis." (PMID 35345660, 2022). "We conclude that miR-144 maybe a potential regulator of the development of atherosclerosis via changes in vimentin signaling." (PMID 32273567, 2020). "Whether the effect of vimentin on ALOX15 promoter activity has an impact on atherosclerosis remain to be determined." (PMID 22879973, 2012). "Thus, vimentin, both in the form of filaments and in a soluble form, is one of the most important links in the molecular processes observed during the course of vascular diseases, atherosclerosis, etc.." (PMID 35453578, 2022). "The expression level of Vimentin, N-cadherin, Snail1, ZEB1, PI3K, p-AKT, p-mTOR and BAX in atherosclerosis and chronic stress were higher than that in control group." (PMID 37642954, 2023). "Furthermore, treatment with CSL311 specifically targeted the upregulation of the Lipid and Atherosclerosis pathway, as identified through KEGG-based GSEA, in the lungs of mice treated with vimentin." (PMID 41476976, 2025). "This study reveals a function of vimentin in CD36 trafficking and macrophage foam cell formation and may guide to establish a new strategy for the treatment of atherosclerosis." (PMID 35656400, 2022). "Further studies will determine whether a new role of vimentin in ALOX15 regulation and the sequence variation at rs2255888 in the ALOX15 is relevant to ALOX15 implication in the pathogenesis of atherosclerosis." (PMID 22879973, 2012).
clear cell renal cell carcinoma (20 papers, 2009 to 2025). "This study demonstrates that immunohistochemical markers, particularly vimentin and Ki-67, can provide clinically meaningful insights into the biological behavior of clear cell renal cell carcinoma." (PMID 40831933, 2025). "In line with our findings, miR-490-3p was found to inhibit vasculogenic mimicry and invasion by targeting the 3′-UTR of vimentin in clear cell renal cell carcinoma cells." (PMID 30886152, 2019). "The presence of prominent sinusoids, hemorrhage, and hemosiderin deposition, as well as the coexpression of cytokeratin and vimentin, strongly suggests a diagnosis of clear cell renal cell carcinoma." (PMID 26600962, 2015). "Vimentin was positive in 53.9% (7/13) cases of clear cell renal cell carcinoma and 80% (8/10) cases of papillary renal cell carcinoma." (PMID 19558708, 2009). "Vimentin was positive in 53.9% cases of clear cell renal cell carcinoma, 80% cases of papillary renal cell carcinoma, focally positive in one case of chromophobe RCC and diffusely positive in another case of chromophobe RCC with sarcomatoid areas." (PMID 19558708, 2009). "Moreover, a recent study confirmed that silencing ENO2 notably reduced the expression levels of EMT markers, including N-cadherin and vimentin, in clear cell renal cell carcinoma (ccRCC)." (PMID 39061144, 2024). "In clear cell renal cell carcinoma, Cripto-1 promoted EMT properties, including the down-regulation of E-cadherin and the up-regulation of Vimentin, N-cadherin, ZEB-1, and Snail." (PMID 34434900, 2021). "We aimed to determine prognostic value of six key EMT markers (CDH1, CDH2, SNAI1, SNAI2, VIM, TWIST1) in clear cell renal cell carcinoma (ccRCC)." (PMID 31915310, 2020). "While vimentin acts as an important structural protein and a known marker of EMT, overexpression of these proteins in patients with poor survival outcomes implies their involvement in EMT and metastasis formation in renal cell clear carcinoma." (PMID 36901940, 2023). "Immunohistochemistry for CD10, vimentin, and renal cell carcinoma antigen were entirely negative, arguing against a collision between an oncocytoma and a high-grade clear cell renal cell carcinoma and supporting a progression of the disease." (PMID 25275525, 2014). "Thus, vimentin and CD10 are expressed only in clear cell renal cell carcinoma; CEA is expressed only in gallbladder carcinomas." (PMID 23305230, 2013). "However despite their sarcomatoid de-differentiation the tumours retained expression of typical clear-cell renal cancer markers such as CD10, pancytokeratin and vimentin positive expression, on a CK-7 negative background (data not shown)." (PMID 20652061, 2010).